EHD4 (EH domain containing 4)
Description:
ATP- and membrane-binding protein that probably controls membrane reorganization/tubulation upon ATP hydrolysis. Plays a role in early endosomal transport. During sprouting angiogenesis, in complex with PACSIN2 and MICALL1, forms recycling endosome-like tubular structure at asymmetric adherens junctions to control CDH5 trafficking (By similarity).
Synonyms: PAST4
Tractability: Antibody: UniProt places it where antibodies can reach, with high confidence; its Gene Ontology location is reachable by antibodies, with medium confidence. PROTAC: ubiquitination databases record sites on it; its protein half-life has been measured.
Gene: Protein-coding gene on chromosome 15 (41,895,933 to 41,972,593, reverse strand). Ensembl gene ENSG00000103966.
Subcellular location: Early endosome membrane; Recycling endosome membrane; Cell membrane; Cell junction, adherens junction
Subcellular location (Human Protein Atlas): Plasma membrane; Primary cilium; Primary cilium transition zone
Gene Ontology:
Molecular function: cadherin binding; protein binding; nucleic acid binding; protein-macromolecule adaptor activity; calcium ion binding; GTP binding
Biological process: endocytic recycling; protein homooligomerization; cell migration involved in sprouting angiogenesis; cilium assembly; protein localization to plasma membrane; cellular response to growth factor stimulus; pinocytosis; regulation of endocytosis
Cellular component: early endosome membrane; endoplasmic reticulum; extracellular exosome; membrane; recycling endosome membrane; adherens junction; early endosome; endocytic vesicle; nucleus; perinuclear region of cytoplasm; plasma membrane
Genetic constraint (gnomAD): Loss-of-function variants: 37 observed, 47.83 expected, observed/expected ratio (o/e) 0.77, 90% interval 0.59 to 1.02. The upper end of that interval is the gene's LOEUF score, 1.02, which puts it in group 4 of 6, group 1 being the genes least tolerant of losing a copy. Missense variants: 632 observed, 718.97 expected, observed/expected ratio (o/e) 0.88, 90% interval 0.82 to 0.94. Synonymous variants: 297 observed, 308.04 expected, observed/expected ratio (o/e) 0.96, 90% interval 0.88 to 1.06.
Homologues: Orthologues: chimpanzee EHD4 (99% identical), macaque EHD4 (99% identical), dog EHD4 (99% identical), pig EHD4 (98% identical), mouse Ehd4 (97% identical), rabbit EHD4 (97% identical), rat Ehd4 (92% identical), tropical clawed frog ehd4 (84% identical), guinea pig EHD4 (84% identical), zebrafish ehd4 (76% identical). Paralogues in human: EHD3 (74% identical), EHD1 (74% identical), EHD2 (69% identical), SRL (24% identical), ITSN1 (21% identical), ITSN2 (19% identical), EPS15 (18% identical), EPS15L1 (18% identical), REPS1 (11% identical), REPS2 (10% identical).
Diseases named in the same sentence as EHD4 in open-access papers:
EHD4 is named in the same sentence as 19 diseases in open-access papers, as found by Europe PMC text mining. Sharing a sentence is not in itself a finding about the gene and the disease. The quoted sentences say what the papers report.
bladder cancer (3 papers, 2017 to 2023). "Another biomarker, EHD4, a member of the Eps15 homology domain-containing protein family, has garnered attention as a potential biomarker in bladder cancer." (PMID 38201450, 2023). "Additionally, NRAS, EHD4, ITGB1 and MUC1, which were among the protein set correlating with bladder cancer on PCA, have been found in various studies of bladder cancer exosomes." (PMID 32249794, 2020).
male infertility (2 papers, 2011 to 2018). The inability of the male to effect fertilization of an ovum after a specified period of unprotected intercourse. "Disruption of endocytosis in EHD4 KO mice results in male infertility similar to that of IP6K1 KO mice." (PMID 29728588, 2018). "Deletion of Ehd1 resulted in small testis with male infertility, while Ehd4 deletion resulted in small testis with moderate reduction in sperm count, indicating a role for EHD1 and EHD4 in male germ cell development/differentiation." (PMID 21408024, 2011).
alcohol addiction (1 paper, 2017). "Moreover, potassium channel genes, such as Kcnma1, which have been implicated in METH and alcohol addiction and genes, such as Eif2s1 and Ehd4, are implicated in drug abuse or reward circuits (Supplemental References)." (PMID 28751711, 2017).
cardiac hypertrophy (1 paper, 2020). "As a main result we found that AGAT−/− mice exhibited altered gene expression related to energy metabolism (Fbp2, Ucp2), cardiac hypertrophy and fibrosis (Nppa, Ctgf), immune response (Fgl2), and the conduction system of the heart (Dsc2, Ehd4, Hcn2, Hcn4, Scn4a, Scn4b)." (PMID 32179820, 2020).
colorectal cancer (1 paper, 2019). A primary or metastatic malignant neoplasm that affects the colon or rectum. "Finally, we found that SMARCA5, MBD3, VPS53, EHD4 are estimated to mediate the regulation of miR-4701-3p and miR-4793-3p on colorectal cancer cell apoptosis, which targets ATP-dependent chromatin remodeling pathway and endocytic recycling pathway." (PMID 31998373, 2019).
glomerular disease (1 paper, 2011). "We generated Ehd3–/–; Ehd4–/– mice to test this hypothesis and observed severe glomerular disease in these mice, demonstrating a critical role for EHD3 and EHD4 in glomerular health." (PMID 21408024, 2011).
hepatocellular carcinoma (1 paper, 2025). A malignant tumor that arises from hepatocytes. "The involvement of EHD4 and PPARGC1A in hepatocellular carcinoma may be mediated by the regulation of tumor-associated macrophages (TAMs) and other immune cells." (PMID 40564032, 2025). "Although this study combined multi-omics data, Mendelian randomization, and animal model systems to reveal the potential role of EHD4 and PPARGC1A in hepatocellular carcinoma, certain limitations remain." (PMID 40564032, 2025). "In summary, genome-wide association studies (GWASs) in recent years still provide relatively limited genetic evidence for EHD4 and PPARGC1A in hepatocellular carcinoma." (PMID 40564032, 2025). "Eventually, our study identified EHD4 and PPARGC1A as key regulators in hepatocellular carcinoma (HCC), particularly through their roles in modulating tumor-associated macrophages (TAMs) and other immune cells within the tumor microenvironment." (PMID 40564032, 2025).
lung carcinoma (1 paper, 2021). "In keeping with the fact that lung cancer cells have more complex genetic landscapes than SCCOHT15,62, only four genes, namely ITPR3, MATN2, EHD4, and ATP2B4, were consistently upregulated by SMARCA4 in both cancer types." (PMID 34518526, 2021).
Stroke (1 paper, 2021). Sudden impairment of blood flow to a part of the brain due to occlusion or rupture of an artery to the brain. "EH-domain-containing 4 (EHD4) is also a protein of the endocytic network that is downregulated both by stroke and treatment with Ngb." (PMID 35008673, 2021).
thrombotic microangiopathy (1 paper, 2011). The syndromes of microangiopathic hemolytic anemia, thrombocytopenia, and variable signs of organ impairment, due to platelet aggregation in the microcirculation. "Detailed analyses of Ehd3–/–; Ehd4–/– kidneys demonstrated thrombotic microangiopathy (TMA)-like glomerular lesions including thickening and duplication of glomerular basement membrane, endothelial swelling and loss of fenestrations." (PMID 21408024, 2011). "H&E and PAS staining of kidney sections from Ehd3–/–; Ehd4–/– mice showed lesions characteristic of thrombotic microangiopathy (TMA)." (PMID 21408024, 2011).
tumor (3 papers, 2020 to 2025). "Our sample results showed that the protein expression of EHD4 is upregulated in HCC tissues compared to non-tumor tissues." (PMID 40564032, 2025). "The positive correlation between EHD4 and M0-type macrophages underscores its potential function in influencing macrophage polarization and promoting tumor progression and immune evasion." (PMID 40564032, 2025). "Decreased EHD2 expression correlates with higher tumor grade and metastasis rates, suggesting that EHD4 may play a role in HCC through a similar mechanism." (PMID 40564032, 2025). "EHD4 may influence the behavior of M0-type macrophages, potentially promoting tumor progression and immune escape by modulating the macrophage endocytosis pathway or the membrane protein recycling process." (PMID 40564032, 2025). "Examination of cluster-specific marker genes showed that tumor ECs expressed a unique set of genes such as Col18a1 and Aplnr, but also shared a number of expressed genes with venous ECs, especially with PV, such as Cd63, Ehd4, and Cd200." (PMID 32440964, 2020). "The results showed that in the TCGA database, EHD4 mRNA expression is significantly upregulated in HCC compared to normal liver tissues, and it is upregulated in tumor tissues with the increase in tumor grade." (PMID 40564032, 2025).
cancer (2 papers, 2021 to 2025). A tumor composed of atypical neoplastic, often pleomorphic cells that invade other tissues. "Another noteworthy aspect is that EHD4 may influence chemotherapy resistance in HCC cells; other members of the EHD family, such as EHD1, have been shown to influence cellular sensitivity to chemotherapeutic drugs in certain cancers by modulating intracellular drug accumulation and efflux." (PMID 40564032, 2025).
bacterial infection (1 paper, 2023). "The studies herein have identified the downstream ISGs TNRFSF10A, PML, MYD88, EHD4, and HK2 that potentiate secondary bacterial infection." (PMID 37939149, 2023).
EHD4 also shares sentences with these, for which no sentence is quoted: arrythmias (1 paper); clear cell carcinoma (1); endometritis (1); influenza (1); liver cancer (1); viral infections (1).